ACTA2 (actin alpha 2, smooth muscle)
Description:
Actins are highly conserved proteins that are involved in various types of cell motility and are ubiquitously expressed in all eukaryotic cells.
Synonyms: ACTSA; SMDYS
Tractability: PROTAC: ubiquitination databases record sites on it.
Gene: Protein-coding gene on chromosome 10 (88,934,822 to 88,991,339, reverse strand). Ensembl gene ENSG00000107796.
Subcellular location: Cytoplasm, cytoskeleton
Subcellular location (Human Protein Atlas): Actin filaments
Pathways (Reactome):
Cell-Cell communication: Activation of STAT3 by cadherin engagement; Regulation of CDH1 Function
Developmental Biology: Developmental Lineage of Mammary Gland Myoepithelial Cells
Extracellular matrix organization: Formation of the dystrophin-glycoprotein complex (DGC)
Muscle contraction: Smooth Muscle Contraction
Signal Transduction: NOTCH4 Intracellular Domain Regulates Transcription
Gene Ontology:
Molecular function: protein binding; ATP hydrolysis activity; protein kinase binding; structural constituent of cytoskeleton
Biological process: glomerular mesangial cell development; response to virus; mesenchyme migration; positive regulation of gene expression; cellular response to transforming growth factor beta stimulus; cytoskeleton organization; juxtaglomerular apparatus development; muscle contraction; positive regulation of ERK1 and ERK2 cascade; positive regulation of hepatic stellate cell activation; positive regulation of hepatic stellate cell contraction; positive regulation of hepatic stellate cell migration
Cellular component: cytoplasm; extracellular exosome; extracellular region; protein-containing complex; actin cytoskeleton; cell body; cytosol; filopodium; lamellipodium; basement membrane; cytoskeleton; motile cilium; smooth muscle contractile fiber; stress fiber
Genetic constraint (gnomAD): Loss-of-function variants: 12 observed, 41.23 expected, observed/expected ratio (o/e) 0.29, 90% interval 0.19 to 0.47. The upper end of that interval is the gene's LOEUF score, 0.47, which puts it in group 2 of 6, group 1 being the genes least tolerant of losing a copy. Missense variants: 236 observed, 526.1 expected, observed/expected ratio (o/e) 0.45, 90% interval 0.4 to 0.5. Synonymous variants: 158 observed, 191.74 expected, observed/expected ratio (o/e) 0.82, 90% interval 0.72 to 0.94.
Gene-disease validity (ClinGen):
ClinGen rates the evidence that ACTA2 causes each of these diseases.
multisystemic smooth muscle dysfunction syndrome (autosomal dominant): Definitive. A spectrum of conditions caused by monoallelic pathogenic variants in ACTA2.
Homologues: Orthologues: dog ACTA2 (100% identical), guinea pig ACTA2 (100% identical), macaque ACTA2 (100% identical), mouse Acta2 (100% identical), pig ACTA2 (100% identical), rabbit ACTA2 (100% identical), rat Acta2 (100% identical), tropical clawed frog acta2 (99% identical), chimpanzee ACTA2 (95% identical). Paralogues in human: ACTG2 (99% identical), ACTC1 (98% identical), ACTA1 (98% identical), ACTG1 (94% identical), ACTB (93% identical), ACTBL2 (88% identical), ACTR1B (54% identical), ACTR1A (54% identical), ACTRT3 (49% identical), ACTRT2 (48% identical), ACTR2 (47% identical), ACTRT1 (47% identical), and 14 more.
Diseases named in the same sentence as ACTA2 in open-access papers:
ACTA2 is named in the same sentence as 259 diseases in open-access papers, as found by Europe PMC text mining. Sharing a sentence is not in itself a finding about the gene and the disease. The quoted sentences say what the papers report.
liver fibrosis (108 papers, 2012 to 2026). "Consistently, elevated serum ALT level reduced significantly after HepG2 EV treatment, which also caused a dramatic attenuation of ACTA2 protein production and reduced expression of liver fibrosis-associated genes including COL1A1 and CCN2." (PMID 40002688, 2025). "ACTA2 has been reported to be associated with the enhancement of hepatic stellate cell contractility, leading to liver fibrosis through the TGF‐β pathway." (PMID 39210544, 2024). "Both treatments caused liver fibrosis associated with an increased expression of Col1a1 and Acta2 in liver tissue." (PMID 39529885, 2024). "IL-5 produced by lung-derived ILC2s can drive eosinophilia while IL-13 can stimulate hepatic stellate cells and induce upregulation of fibrosis-associated genes including Col1a1, Acta2 and Timp1, thus promoting liver fibrosis." (PMID 34305911, 2021). "Another study showed that PTEN-deficient mice develop progressive liver fibrosis characterised by the increased expression of ACTA2, COL1 and tissue inhibitor of matrix metalloproteinase (TIMP)-1." (PMID 34648138, 2021). "After long-term palmitate injection, the BD-fed mice showed mild liver fibrosis by sirius red staining and alpha-smooth muscle actin (αSMA, encoded by Acta2) expression." (PMID 30054551, 2018). "Finally, the analysis of individual transcripts showed that many putative genes associated with liver fibrosis such as Acta2, Col1a1, Lox and Hhipl1 were upregulated in animals fed with SSD." (PMID 37774007, 2023). "Hepatic fibrosis markers (Acta2 and Col1a1) and collagen deposition remained elevated in Tet2ΔMye-CCl4 mice despite IL-1β neutralization." (PMID 41474968, 2026). "On the other hand, Cyp4a14 gene overexpression reduced liver fibrosis markers such as Tgfb1 and Acta2 in a model of cholestatic liver fibrosis." (PMID 41180305, 2025). "Collagen proportionate area (CPA), hydroxyproline quantification, and assessment of fibrogenic gene expression (Acta2, Col1a, Tgfb1, and Timp1) showed a minor effect of Prdx2 KO on liver fibrosis." (PMID 40932790, 2025). "In contrast, aged mice exhibited hepatic fibrosis, with increased collagen deposition and upregulation of genes related to fibrosis (Acta2, MMP2, TGF-ß1, and Col1a2), cirrhosis (CXCR4, SOX9, DCN, and MFAP4), and cancer (Bcl2, CDKN2a, c-Myc, and Fn1)." (PMID 39851554, 2025). "A recent study demonstrated that a long-term (12 weeks) exposure to NMPLs induces liver fibrosis in mice, with increased expression of the α-smooth muscle actin (ACTA2) gene." (PMID 41154647, 2025). "Fibrosis progression in the NASH mouse model was assessed by measuring the relative gene expression levels of liver fibrosis markers, specifically Col1a1 and Acta2, as well as the inflammation marker Mcp1, using RT-qPCR." (PMID 39894410, 2025). "Specifically, 680 proteins in cluster 1, including pro- and anti-inflammatory cytokines (e.g., IL-6 and IL-10) and liver fibrosis markers (e.g., ACTA2, KRT19, and SPP1), increased progressively with fibrosis stages." (PMID 39889710, 2025). "Treatment with α4β7 mAb reduced hepatic fibrosis reflected by decreased collagen deposition in the liver and significant reduction in the transcript levels of Acta2, Col1a1, Col1a2, Tgfb1 and Timp1." (PMID 38727292, 2024). "Quantitative real-time polymerase chain reaction (qRT-PCR) elucidated the downregulation of key hepatic fibrosis markers (ACTA2, COL1A1, and SMAD2) upon exposure to crude KL extract." (PMID 39062514, 2024). "Transcriptional levels of liver fibrosis markers (ACTA2, COL1A1, COL1A2, COL3A1) and ductular reaction markers (EPCAM, KRT7, KRT19) were significantly upregulated in BA." (PMID 36816373, 2023). "Firstly, liver fibrosis (marker as ACTA2, COL1A1, COL1A2, COL3A1), reflected by proliferation of myofibroblasts and collagen deposition, is associated with decreased native liver survival mostly." (PMID 36816373, 2023).
liver fibrosis (continued). "The mRNA expression of collagen 1α1 (Col1α1) and ACTA2—markers of liver fibrosis—also increased with cholesterol load." (PMID 37902528, 2023). "CTGF silencing in liver fibrosis rodent models has shown to cause a decrease in the transcription of TGFB1, ACTA2 and COL1A1." (PMID 36672237, 2023). "The validation cohort showed GPC3 was negatively correlated with all liver fibrosis markers ACTA2, COL1A1, COL1A2, COL3A1 and ductular reaction markers KRT7 and KRT19, while SDC4 was positively correlated with ductular reaction index KRT19." (PMID 36816373, 2023). "These NASH liver organoids showed the appearance of cells with dendritic-like morphology and the increased expression of liver fibrosis-related genes such as Collagen type I alpha 1 (Col1a1), Actin alpha 2 (Acta2), and others." (PMID 37900170, 2023). "Consistently, hepatic expression levels of genes, including a progenitor cell marker (Sox9), a liver fibrosis marker (Acta2), and an inflammation marker (Il6), were decreased in Sesn1−/−-BDL vs." (PMID 34880414, 2022). "Liver SCTR expression localized in cholangiocytes and correlated positively with liver fibrosis, DR, and transcriptional markers of fibrosis (ACTA2) and cholangiocytes (KRT7, KRT19) both at PE and after SPE." (PMID 35508528, 2022). "The key players in liver fibrosis are hepatic stellate cells (HSCs), which produce α-smooth muscle actin (αSMA; Acta2) and other extracellular matrix components." (PMID 34959755, 2021). "The level of fibrosis‐related genes (Acta2, Col1a1 and Timp1) was increased in liver injury groups for 10 weeks compared to 4 and 6 weeks, which confirmed the extent of liver fibrosis evaluated by fibrosis score." (PMID 33410581, 2021). "In line with decreased liver fibrosis and injury in Oxy210‐fed mice, hepatic expression of collagen (Col1a1) and α‐smooth muscle actin (Acta2) were substantially reduced." (PMID 34505423, 2021). "The presence of liver fibrosis was evaluated by Sirius-red-stained collagen-1α1 deposition and alpha-smooth muscle actin (αSMA, ACTA2)-stained activated stellate cells." (PMID 34943832, 2021). "Similar results were shown in our CCl4 induced liver fibrosis model, as ACTA-2, TIMP-2 and Collagen-1 mRNA expression and Sirius red and α-SMA staining were similar between TLR4 KO and WT mice." (PMID 33391458, 2021). "Similar to the CCl4 model, Treg cells significantly were increased in the liver by feeding the diet and Treg depletion aggravated liver fibrosis assessed by liver fibrotic regions and expression levels of Col1a1 and Acta2 (α-SMA)." (PMID 33178216, 2020). "As expected, the levels of ALT and AST, two typical serum markers of liver injury, the expression of ACTA2, and levels of collagen deposition all were increased in rats with CCl4-induced liver fibrosis." (PMID 32210801, 2020). "The observed sevelamer-mediated attenuation of hepatic fibrosis coincided with a decline in the hepatic expression levels of profibrotic genes including Col1a1, Acta2, and Tgfb1." (PMID 32575352, 2020). "Consistent with previously published data, MRTF-A deletion attenuated liver fibrosis as indicated by the down-regulation of α-SMA (Acta2) expression." (PMID 31681772, 2019). "We found that 0.06% TAA treatment induced liver fibrosis, characterised by increased RNA expression of collagen, Hand-2 and Acta-2, smaller liver sizes and collagen deposition." (PMID 30375438, 2018). "Considering CDAA diet-induced hepatic fibrosis, nicotine administration attenuated hepatic fibrosis, Acta2 mRNA levels, and α-SMA positive cells." (PMID 28662136, 2017).
liver fibrosis (continued). "Similarly, the levels of mRNA related to liver fibrosis (Col1A1, Acta2, Timp1, and Tgfb1) were significantly increased in the DM group, which were significantly reduced by the LFD treatment." (PMID 41374037, 2025). "Furthermore, we examined the relative mRNA expression levels of key markers related to hepatic fibrosis (Acta2, Cola2, TGF-β1, and MMP2), cirrhosis (CXCR4, SOX9, DCN, and MFAP4), and cancer (Bcl2, CDKN2a, c-Myc, and Fn1) across the experimental groups." (PMID 39851554, 2025). "Our study revealed that AURKA expression increases with the progression of liver fibrosis and is positively correlated with ACTA2, a marker of activated HSCs, as well as the fibrogenic genes COL1A1 and TIMP1, based on publicly available gene expression datasets from liver fibrosis patients." (PMID 39834933, 2024). "As anticipated, image analysis of IF-stained α-smooth muscle actin (α-SMA, encoded by the ACTA2 gene), a common HSC activation marker associated with hepatic fibrosis, revealed an increase of α-SMA stress fibers upon treatment with TGF-β alone and in combination with starvation." (PMID 39044210, 2024). "HSC activation, marked by high expression of Acta2, is a core step for liver fibrosis." (PMID 37860111, 2023). "The mRNA levels of liver fibrosis markers (Acta2, Col1a1, Col3a1, and Timp1), cholangiocyte proliferation markers (Krt7 and Krt19), inflammation markers (Il6 and Il1b), and the progenitor cell marker (Sox9) were markedly decreased in miR-200c-BDL mice compared to con-BDL mice." (PMID 34880414, 2022). "Also, incubating LX2 cells with either GDF11 or TGF-β for 24 h led to significantly elevated mRNA levels of MMP2, αSMA/ACTA2, Col1A1 and Col5A1 — markers for stellate cell activation and liver fibrosis." (PMID 33126224, 2020). "The results showed that the collagen deposition and liver fibrosis caused by S. japonicum infection were markedly alleviated after DKK1 treatment, which was accompanied by a decrease in the expression of α-SMA/Acta2, desmin and Col1a1." (PMID 28331224, 2017). "Subsequently, transcript levels of genes associated with hepatic fibrosis were assessed via qRT-PCR, which revealed a significant upregulation of fibrosis-related transcripts encoding proteins such as procollagen α1(I), TIMP-1, α-SMA (ACTA2), MMP-2, and MMP-9 in the livers of scurfy mice." (PMID 37818371, 2023). "Furthermore, hepatic mRNA levels of fibrogenic genes (Acta2, Col1a1, Col3a1, Col4a1, Tgfb1, Mmp13 and Vim) were significantly upregulated in miR-223KO mice compared with WT mice, suggesting that miR-223 deletion accelerated liver fibrosis." (PMID 33867837, 2021). "Furthermore, the mRNA and protein levels of hepatic markers that could be used to determine the degree of liver fibrosis, such as Acta2, Col1a1 and Fn1 were markedly elevated by CCl4 but inhibited by SWT in different doses." (PMID 34736501, 2021). "The molecules, including Scd1, Acta2, collagen type I alpha 1 chain (Col1a1), Timp1, Foxm1, Sult1e1, and plasminogen activator (Plat), are also involved in hepatotoxicity pathways, such as liver fibrosis, liver hyperplasia/hyperproliferation, liver proliferation, and liver necrosis/cell death." (PMID 34539442, 2021). "In line with this, iNOS deletion significantly reduced the activation of HSCs as confirmed by the reduced gene expression levels of both Tgfb and a-SMA (Acta2), suggesting that iNOS deficiency could regress the activation of HSC by interfering with the TGF-β pathway, protecting from liver fibrosis." (PMID 30818874, 2019). "Liver fibrosis is a response to chronic liver injury that involves the accumulation of extracellular matrix (ECM) components, such as type I collagen, ACTA2 (Actin Alpha 2, Smooth Muscle), fibronectin and hyaluronic acid." (PMID 40244247, 2025). "In human HBV-related liver fibrosis, genes such as COL1A1, TIMP1, ACTA2, and CTGF are consistently upregulated, reflecting structural reorganization and inflammatory signaling cascades." (PMID 41586310, 2025).
liver fibrosis (continued). "ICA was reported to reduce the expressions of Col1a1 and Acta2 in the livers from CCl4‐challenged mice and ameliorate thioacetamide (TAA)‐induced liver fibrosis in rats by inhibiting hepatic Col1a1 expression and collagen deposition." (PMID 39501714, 2024). "In line with the progressive damage, DEN potentiated hepatic fibrosis in rats fed the ATH diet compared to the CD feeding, as seen by the increase in the expression of Col1a1, Acta2, and Tgfβ, and Sirius red staining, as well as α-SMA." (PMID 34439245, 2021). "For Acta2, male MDR2 knockout mice tended to have a more pronounced reversal of liver fibrosis than females treated with corticosterone." (PMID 32582715, 2020). "In line with the histological analysis, results from the mRNA expression of pro-fibrotic genes (including Acta2, Col1a1, Col1a2, and Tgfb1) further demonstrated that prophylactic but not therapeutic administration of OCA were effective against liver fibrosis." (PMID 31932588, 2020). "An in vitro study showed that IL-17A enhances the expression of pro-fibrotic genes (e.g., ACTA2 and COL1A1) by hepatic stellate cells through JNK-dependent up-regulation of TGF-β receptor on these cells, providing a possible mechanism for liver fibrosis." (PMID 33013934, 2020). "On the contrary, ecKOm/m LSECs expressed lower levels of Col1a2 (encoding Collagen type I) and Acta2 (encoding α-SMA), two prominent mesenchymal markers, compared to WT LSECs, suggesting that MKL1 deficiency in endothelial may alleviate EndMT in the context of liver fibrosis in vivo." (PMID 31776330, 2019). "Meanwhile, the mRNA expression levels of Acta2, MMP13, Coll1a1, and TIMP1 were examined, which are all classical profibrogenic markers during liver fibrosis process." (PMID 29464186, 2017). "Another gene involved in liver fibrosis, that is ‘actin alpha 2’ (Acta2), trended towards an elevated expression in mice lacking Mir26b." (PMID 40261813, 2025). "Mice lacking Acta2 exhibited significantly less liver fibrosis after chronic injury, indicating a critical role of this gene in fibrogenesis." (PMID 41162675, 2025). "Lack of Surf4 also significantly reduced the expression of liver fibrosis markers (Col1a, Acta2/α-Sma) and inflammation markers (Il-1β and Tnf-α) at mRNA and protein levels in male and female Surf4LKO mice." (PMID 39105051, 2024). "Similarly, the expressions of the genesCOL1A1,COL3A1,ACTA2,DES,TGFβ1, andVIM, which are involved in liver fibrosis, increased in liver organoids treated with 100 mM and 200 mM ethanol." (PMID 38818583, 2024). "Thus, our subcluster analysis revealed the presence of at least four phenotypes of HSCs during liver fibrosis, namely myeloid myofibroblasts (HSC0), resting HSCs (HSC1), Clec3b+ HSCs (HSC2), and myofibroblasts with high expression of Acta2 (HSC3)." (PMID 37724132, 2023). "Liver fibrosis levels, indicated by Col1a1 and Acta2 expression, and hepatic collagen levels were not different." (PMID 37626991, 2023). "Importantly, Cdk2ΔHSC mice showed a significant reduction of hepatic fibrosis compared to WT controls as determined by Sirius Red staining of fibers and measurement of HSC activation markers Acta2 and Col1a1." (PMID 37620309, 2023). "The results of Masson staining showed the reduction of collagen deposition in Zbp1 siRNA-GeRP-treated injured livers, which was in accordance with the decreases of Acta2 (α-SMA, the marker of liver fibrosis), Col1a1 (Col I) and Col3a1 expressions in Zbp1 siRNA-GeRPs-injection groups." (PMID 36859525, 2023). "Detection of the mRNA levels of a series of liver fibrosis-related molecules: Acta2, Col1a1, Tgfb1, and Timp1 in livers from IL-21−/−p40−/−IL-2Ra−/− mice and controls suggested no significant change of liver fibrosis." (PMID 35300072, 2022).